SMAD2 (SMAD family member 2)
Description:
Receptor-regulated SMAD (R-SMAD) that is an intracellular signal transducer and transcriptional modulator activated by TGF-beta (transforming growth factor) and activin type 1 receptor kinases. Binds the TRE element in the promoter region of many genes that are regulated by TGF-beta and, on formation of the SMAD2/SMAD4 complex, activates transcription. Promotes TGFB1-mediated transcription of odontoblastic differentiation genes in dental papilla cells (By similarity). Positively regulates PDPK1 kinase activity by stimulating its dissociation from the 14-3-3 protein YWHAQ which acts as a negative regulator. May act as a tumor suppressor in colorectal carcinoma.
Synonyms: hSMAD2; hMAD-2; MADH2; MADR2; JV18-1; CHTD8; JV18; LDS6
Tractability: Small molecule: a high-quality ligand is known; it has a binding pocket of medium quality. PROTAC: UniProt records ubiquitination sites on it; ubiquitination databases record sites on it; its protein half-life has been measured; a small molecule that binds it is known.
Target class: Transcription factor
Gene: Protein-coding gene on chromosome 18 (47,808,957 to 47,931,569, reverse strand). Ensembl gene ENSG00000175387.
Subcellular location: Cytoplasm; Nucleus
Subcellular location (Human Protein Atlas): Nucleoli; Nucleoplasm; Cytosol; Primary cilium transition zone; Vesicles
Pathways (Reactome):
Developmental Biology: Formation of axial mesoderm; Formation of definitive endoderm; Germ layer formation at gastrulation; Signaling by NODAL; Transcriptional regulation of pluripotent stem cells
Signal Transduction: Downregulation of SMAD2/3:SMAD4 transcriptional activity; Downregulation of TGF-beta receptor signaling; SMAD2/SMAD3:SMAD4 heterotrimer regulates transcription; Signaling by Activin; TGF-beta receptor signaling activates SMADs
Disease: SMAD2/3 MH2 Domain Mutants in Cancer; SMAD2/3 Phosphorylation Motif Mutants in Cancer; SMAD4 MH2 Domain Mutants in Cancer; TGFBR1 KD Mutants in Cancer
Gene expression (Transcription): FOXO-mediated transcription of cell cycle genes; FOXO-mediated transcription of oxidative stress, metabolic and neuronal genes
Metabolism of proteins: Ub-specific processing proteases
Gene Ontology:
Molecular function: co-SMAD binding; disordered domain specific binding; DNA binding; DNA-binding transcription activator activity, RNA polymerase II-specific; DNA-binding transcription factor activity; DNA-binding transcription factor binding; I-SMAD binding; identical protein binding; phosphatase binding; protein binding; R-SMAD binding; RNA polymerase II cis-regulatory region sequence-specific DNA binding; SMAD binding; transforming growth factor beta receptor binding; type I transforming growth factor beta receptor binding; ubiquitin protein ligase binding; cis-regulatory region sequence-specific DNA binding; DNA-binding transcription factor activity, RNA polymerase II-specific; double-stranded DNA binding; tau protein binding; chromatin binding; RNA polymerase II-specific DNA-binding transcription factor binding
Biological process: activin receptor signaling pathway; determination of left/right asymmetry in lateral mesoderm; negative regulation of DNA-templated transcription; negative regulation of ossification; nodal signaling pathway; positive regulation of BMP signaling pathway; positive regulation of DNA-templated transcription; positive regulation of transcription by RNA polymerase II; regulation of transforming growth factor beta receptor signaling pathway; response to cholesterol; SMAD protein signal transduction; transforming growth factor beta receptor signaling pathway; trophoblast cell migration; zygotic specification of dorsal/ventral axis; anatomical structure morphogenesis; anterior/posterior pattern specification; aortic valve morphogenesis; cell differentiation; cell fate commitment; DNA-templated transcription; endocardial cushion morphogenesis; gastrulation; intracellular signal transduction; mesoderm formation; negative regulation of cell differentiation; and 14 more
Cellular component: activin responsive factor complex; chromatin; cytoplasm; cytosol; heteromeric SMAD protein complex; homomeric SMAD protein complex; nucleolus; nucleoplasm; nucleus; protein-containing complex; SMAD protein complex; transcription regulator complex
Genetic constraint (gnomAD): Loss-of-function variants: 6 observed, 47.51 expected, observed/expected ratio (o/e) 0.13, 90% interval 0.068 to 0.25. The upper end of that interval is the gene's LOEUF score, 0.25, which puts it in group 1 of 6, group 1 being the genes least tolerant of losing a copy. Missense variants: 198 observed, 461.33 expected, observed/expected ratio (o/e) 0.43, 90% interval 0.38 to 0.48. Synonymous variants: 161 observed, 163.63 expected, observed/expected ratio (o/e) 0.98, 90% interval 0.87 to 1.12.
Gene-disease validity (ClinGen):
ClinGen rates the evidence that SMAD2 causes each of these diseases.
congenital heart disease (autosomal dominant): Definitive. A heart disease that is present at birth.
Loeys-Dietz syndrome 6 (autosomal dominant): Definitive.
Cancer hallmarks: invasion and metastasis (suppresses); suppression of growth (promotes); cell replicative immortality (promotes); escaping programmed cell death (suppresses)
Homologues: Orthologues: chimpanzee SMAD2 (100% identical), guinea pig SMAD2 (100% identical), macaque SMAD2 (100% identical), pig SMAD2 (100% identical), rabbit SMAD2 (100% identical), tropical clawed frog smad2 (99% identical), mouse Smad2 (94% identical), rat Smad2 (85% identical). Paralogues in human: SMAD3 (84% identical), SMAD1 (61% identical), SMAD5 (61% identical), SMAD9 (60% identical), SMAD4 (41% identical), SMAD6 (25% identical), SMAD7 (22% identical).
Diseases named in the same sentence as SMAD2 in open-access papers:
SMAD2 is named in the same sentence as 389 diseases in open-access papers, as found by Europe PMC text mining. Sharing a sentence is not in itself a finding about the gene and the disease. The quoted sentences say what the papers report.
breast carcinoma (223 papers, 2005 to 2026). "High PFN2 expression has also been linked to poor prognosis in breast cancer, where it facilitates metastasis through Smad2 upregulation." (PMID 41395115, 2025). "Administering FAKi and genetically rendering FAK deficient in breast cancer cells abrogated the interaction between TGFβRI and TGFβRII and thereby blocked phosphorylation of Smad2 and expression of its downstream effector PTHLH." (PMID 35538070, 2022). "miRNAs (miR-29a and miR-140, miR-148a) can be an effective diagnostic and prognostic marker as they regulate SMAD4 and SMAD2 expression respectively in breast cancer blood and biopsy samples." (PMID 34297787, 2021). "TrkB expression is significantly increased in tissues obtained from breast cancer patients relative to normal breast tissue, with TrkB strongly associating with SMAD2, SMAD3, and SMAD4." (PMID 32340410, 2020). "Although recent work has shown that TGF‐β induced UCA1 expression in breast cancer through downstream Smad2/3 signaling 20, the detailed mechanisms underlying Smad2/3‐mediated regulating of UCA1 expression were not revealed." (PMID 30410864, 2018). "miR-190 expression is down-regulated and inversely correlates with SMAD2 in breast cancer samples, and its expression level was associated with outcome in patients with breast cancer." (PMID 29510731, 2018). "Lastly, Mts-4 QTL candidate gene, Smad2, underlies Smad2-dependent epithelial mesenchymal transition of breast cancer cells, a key step in invasiveness and subsequent metastasis." (PMID 23967281, 2013). "Consistent with the current finding, previous studies on esophageal squamous cell carcinoma, breast cancer and colorectal cancer demonstrated that loss of Smad2 expression is correlated with tumor development and poor prognosis." (PMID 22539990, 2012). "Array analysis revealed among other genes that CRF induced the expression of SMAD2 and β-catenin, genes involved in breast cancer cell proliferation and cytoskeletal changes associated with metastasis." (PMID 20875132, 2010). "To investigate the merits of this supposition, we compared the ability of control and FAK-deficient metastatic breast cancer cells to activate Smad2/3 and p38 MAPK in response to TGF-β." (PMID 19740433, 2009). "A limited number of studies investigated the prognostic relevance of phosphorylated SMAD2 (pSMAD2) as an indicator of active TGF-β signaling in diagnostic breast cancer tissues, with both suggesting an adverse prognosis and an increased risk of disease recurrence." (PMID 40488800, 2025). "Given that canonical and non-canonical TGFβ pathways affect chromatin accessibility and that CDK4/6 inhibition induces chromatin remodelling by enhancer activation in breast cancer, SMAD2 splice variants and corresponding phospho-isoforms are critical modulators of gene transcription in NSCLC." (PMID 40319202, 2025). "Thus, SMAD2 may play a key role in regulating Tn antigen expression in proteins such as MUC-1 that are associated with breast cancer progression." (PMID 34367349, 2021). "High-level correlation between PUS7 and three key stemness-related genes (SMAD2, c-Myc, EpCAM) was further revealed in breast cancer and TNBC patients through TIMER analysis." (PMID 41554761, 2026). "A previous study of human mammary carcinoma-derived CAFs demonstrated that autocrine TGF-β signaling can upregulate CXCL12 expression through Smad2/3 activation." (PMID 40849508, 2025). "This study examined the impact of active TGF-β signaling on recurrence and radiotherapy (RT) benefit in early-stage breast cancer, using nuclear phosphorylated Smad2 (pSMAD2) as a marker for pathway activation." (PMID 40488800, 2025). "Further, the fluorescence imaging demonstrated that the SMAD2‐silenced mouse suffered more serious breast cancer bone metastasis in the femur, tibia, and vertebra, however, the SMAD3‐silenced mouse presented a contrast result." (PMID 39947253, 2025).
breast carcinoma (continued). "At present, research has shown that PI3K inhibitors can block the phosphorylation of Smad2 in breast cancer cells, which indicates that Smad2 protein is the downstream target of the PI3K pathway." (PMID 40149435, 2025). "Immunofluorescence imaging revealed an enhanced fluorescent signal of phosphorylated Smad2/Smad3 in breast cancer cells after 3oc treatment, and these fluorescent signals were mainly located in the nucleus." (PMID 39786928, 2025). "In mammary carcinoma-associated fibroblasts, TGF-β negatively regulates CXCL1 expression through Smad2/3 and HGF/c-Met signaling mechanisms." (PMID 40490643, 2025). "In contrast to our findings in pancreatic CAFs, authors showed that SMAD2/3 phosphorylation was unaffected upon myoferlin silencing but revealed an impact of myoferlin on TGFß secretion and autocrine signaling in breast cancer cell lines." (PMID 41062852, 2025). "A similar effect of Smad2 on tumor angiogenesis was reported in breast cancer cells, in which Smad2 suppressed the expression of vascular endothelial growth factor A, a crucial promoter of tumor angiogenesis." (PMID 38569937, 2024). "Next, we determined activation of the p38 and Smad2/3 signaling pathways in response to TGF-β/TNF-α co-stimulation in MDA-MB-231 breast cancer cells." (PMID 39351229, 2024). "A potential region of SMAD3 binding within an intron of C1orf106 was identified in a SMAD2/3 ChIP-sequencing analysis of TGF-β target genes in MII breast cancer cells." (PMID 39329715, 2024). "hsa-miR-190 was found to target SMAD2 (Mothers against decapentaplegic homolog 2) and suppress metastasis in breast cancer via regulation of TGF-β induced EMT." (PMID 39595529, 2024). "For example, Transcriptional activity of SMAD2/SMAD3:SMAD4 heterotrimer involved in the degradation of SKI/SKIL, thus causing malignant transformation in breast cancer." (PMID 38652712, 2024). "We further demonstrate that TGF-β priming and Smad2/3 signaling drive synergy with TNF-α to promote MMP-9 expression in breast cancer cells." (PMID 39351229, 2024). "Kaempferol induces the cell cycle at the G2/M phase in MDA-MB-453 breast cancer cells and reverses the EMT process in gastric, ovarian, and breast cancer cells by modulating key markers such as E-cadherin, Smad2/4, TGF-β, N-cadherin, vimentin, and Snai1." (PMID 39275063, 2024). "TFAP2A-AS1 is a tumor suppressor of breast cancer as it competes for miR-933, thereby releasing SMAD2." (PMID 37808187, 2023). "Among these stemness-related genes, the top 3 genes positively correlated with NOLC1 were MYC, ALDH18A1, and SMAD2 in breast cancer when analyzed using the TIMER2.0 database." (PMID 35174077, 2022). "Limiting our comparisons to genome interval files derived from mammary or breast cancer cells, we observed that similarity scores for SMAD2/3 occupancy patterns diminished over the time course of treatment." (PMID 35008373, 2022). "In this study, we first validated a LAP-tagged R-Smad system that enables identification of Smad2- and Smad3-specific binding sites in a breast cancer cell line." (PMID 35858839, 2022). "PICK1 inhibits the processing of pre-mir-615-3p to mature miR-615-3p via interfering with the binding of DICER1 to Smad2/3 in breast cancer cells." (PMID 35183226, 2022). "A similar inhibition of SMAD2 phosphorylation by dMSN‐SB was also observed in Hs766T human pancreatic cancer cells and 4T1 murine breast cancer cells." (PMID 35128843, 2022). "In particular, UCHL1 promotes TGF-β signal transduction by acting on the TGF-β signaling pathway and Smad2 signaling pathway, thus inducing breast cancer cell metastasis." (PMID 35546675, 2022). "In order to experimentally distinguish Smad2 and Smad3 target sites, Smad2 and Smad3 fusion proteins were transfected into the breast cancer cell line MDA-MB-231 in a native cis-regulatory environment as BAC transgenes." (PMID 35858839, 2022).
breast carcinoma (continued). "The protein level of p-SMAD2/3 was increased in irradiated breast cancer cell lines but was decreased by combination treatment with vactosertib and radiation." (PMID 36167880, 2022). "TGFβ1-mediated activation of SMAD2/3/4 induced transcriptional upregulation of HOTAIR in breast cancer cells." (PMID 33511320, 2021). "In conclusion, our study revealed that the activation of ER stress inhibited the VM phenotype of breast cancer cells via both the TGF‐β1/Smad2/3 and β‐catenin signaling pathways." (PMID 34320274, 2021). "SMAD2 gene, miR-140, and miR-148a expression patterns were found correlating between blood and biopsy samples of breast cancer patients." (PMID 34297787, 2021). "The altered protein levels of Smad2 and Smad3 were observed in several type of cancers, including breast cancer, compared to normal mammary epithelial cells." (PMID 33809098, 2021). "For example, circPGR was recently found to function as a ceRNA to promote estrogen receptor-positive breast cancer cell growth; our recent study found that hsa_circ_0001829 functions as an oncogene in GC and exerts its effects via miR-155-5p/SMAD2 axis." (PMID 34162830, 2021). "We showed that similarly to other studies using breast cancer-derived cells, the blockage between both signaling pathways is because E2 decreases the Smad2 and Smad3 proteins expression." (PMID 33925221, 2021). "Glabridin is an isoflavane present in the root extract of licorice (Glycyrrhiza glabra) that was effective in reducing the cancer stem cell-like properties through the miRNA-148a/ TGFβ-SMAD2 pathway in human breast cancer cells both in vitro and in vivo." (PMID 33498521, 2021). "The data suggest that the activation of ER stress inhibited VM phenotype formation of breast cancer cells via both the transforming growth factor β1/Smad2/3 and β‐catenin signaling pathways." (PMID 34320274, 2021). "Here, higher SMAD2/3 levels were detected in primary mammary tumors derived from the double transgenic mice (i.e., MMTV–Prune-1/Wnt1), compared with those from MMTV–Wnt1 models." (PMID 33426510, 2021). "At the same time, to clarify the correlation between miR-3613-3p and SMAD2/EZH2 in breast cancer, we tested tissue samples from cancer lesions and adjacent non-cancerous areas by using qRT-PCR and Western blotting." (PMID 33330073, 2020). "TGF-β secreted by Treg cells up-regulates IL-17RB on 4T1 and EMT6 murine breast cancer cells via Smad2/3/4 signaling and increases their tumor growth and metastatic potential in vivo." (PMID 32373132, 2020). "miR-503-3p promotes epithelial-mesenchymal transition in breast cancer by directly targeting SMAD2 and E-cadherin." (PMID 32711579, 2020). "Administration of curcuminoids (25 and 50 mg/kg) suppresses breast cancer malignancy via inhibiting phosphorylation of Smad2 and Smad3." (PMID 33381035, 2020). "We found that TGF-β1 activated phosphorylation of Smad2/3 and induced Smad2/3 nuclear translocation in breast cancer cells; and both Smad2/3 phosphorylation and nuclear translocation were significantly inhibited by emodin." (PMID 32724475, 2020). "SMAD2 is overexpressed in breast cancer tissues and plays an important part in the promotion of tumor progression." (PMID 33330073, 2020). "Treatment with SB525334 (TGF-β type I receptor inhibitor) or chemerin rescued the expression of E-cadherin detected along the plasma membranes and inhibited the translocation of β-catenin and SMAD2/3 into the nucleus in TGF-β-treated breast cancer cells." (PMID 32325994, 2020). "The Shanghai Breast Cancer Study suggested that the expression of p-Smad2 and TβRII in the cytoplasm is predominantly correlated with an invasive histological type and with poor prognosis in breast cancer patients." (PMID 31408934, 2019). "Blocking the binding of TGF‐β to its receptor by special inhibitor attenuates MMP‐9‐induced phosphorylation of SMAD2/3 and the increases in SMADs in the breast cancer cells." (PMID 31264317, 2019).